SNORD116-26 (small nucleolar RNA, C/D box 116-26)
Synonyms: HBII-85-26
Gene: Small nucleolar RNA gene on chromosome 15 (25,099,499 to 25,099,594, forward strand). Ensembl gene ENSG00000251815.
Gene Ontology:
Biological process: RNA processing
Cellular component: nucleolus
Homologues: Orthologues: macaque SNORD116 (99% identical), mouse Gm22373 (55% identical), rat LOC120100337 (45% identical). Paralogues in human: SNORD116-25 (91% identical), SNORD116-27 (82% identical), SNORD116-30 (76% identical), SNORD116-2 (71% identical), SNORD116-29 (71% identical), SNORD116-6 (71% identical), SNORD116-16 (70% identical), SNORD116-8 (70% identical), SNORD116-20 (69% identical), SNORD116-23 (69% identical), SNORD116-24 (69% identical), SNORD116-28 (69% identical), and 20 more.